LONP1 (lon peptidase 1, mitochondrial)
Diseases named in the same sentence as LONP1 in open-access papers (continued):
Sharing a sentence is not in itself a finding about the gene and the disease.
hepatic cancer (1 paper, 2019). "Most important, our results confirmed that two protein markers Lonp1 and Ogdh based on mtFE readouts also remain significantly dysregulated and predictive in the classification of hepatic cancer tissue." (PMID 31061415, 2019). "Summary statistics calculated for markers that were validated in CD-HFD mice cohort 3, showed Lonp1 and Ogdh mtFE protein scores to be strongly predictive to NASH-induced mouse model of liver cancer." (PMID 31061415, 2019).
hyperandrogenism (1 paper, 2023). Excessive secretion of androgens from the adrenal glands or gonads. "In this study, we found that LONP1 Kcr was significantly down‐regulated in the peripheral blood of PCOS patients with hyperandrogenism." (PMID 37817894, 2023).
MELAS (1 paper, 2017). "The levels of LONP1 were increased in all mutant cybrid lines with exception of m.Trp cells, expression of AFG3L2 was induced in all disease cell models except MELAS, and the levels of CLPP were increased in MELAS, m.Val and m.ND6 cells, whereas they were reduced in MERRF and m.Trp cells." (PMID 28740091, 2017).
metabolic syndrome (1 paper, 2023). A cluster of metabolic risk factors for CARDIOVASCULAR DISEASES and TYPE 2 DIABETES MELLITUS. "Further studies will allow us to determine the specific role of Lonp1 in the pathogenesis of each of the components of the metabolic syndrome (and their combination) and to develop drugs based on the Lonp1 protease, similar to the described new anticancer drugs targeting AAA + proteases." (PMID 37569389, 2023). "Thus, LonP1 protease may play a key role in the pathogenesis of metabolic syndrome and indirectly regulate the magnitude of the inflammatory response, providing a potential target for the prevention of complications of the disease." (PMID 37569389, 2023). "The aim of this review is to elucidate the role of mtDNA in the pathogenesis of metabolic syndrome and its components as a key component of mitochondrial dysfunction and to describe the promising and little-studied AAA + LonP1 protease as a potential target in metabolic disorders." (PMID 37569389, 2023).
mitochondrial cytopathy (1 paper, 2022). "The top GWAS hit is a missense mutation in LONP1, which encodes a mitochondrial protease that has been shown to cause mitochondrial cytopathy and reduced respiratory chain activity." (PMID 34859289, 2022).
myocardial infarct (1 paper, 2023). "Furthermore, myocardial infarct size post I/R injury was significantly larger in Lonp1+/−, and significantly smaller in transgenic mice overexpressing Lonp1." (PMID 36978846, 2023).
neutropenia (1 paper, 2022). A decrease in the number of neutrophils found in the blood. "Dysfunction of the three AAA+ unfoldases CLPX, CLPB, and LONP1 causes distinctive features in peripheral tissues such as deficient heme biosynthesis, neutropenia, and collagen networks, respectively." (PMID 35954215, 2022).
non-small cell lung carcinoma (1 paper, 2021). A group of at least three distinct histological types of lung cancer, including non-small cell squamous cell carcinoma, adenocarcinoma, and large cell carcinoma. "LonP1 knockdown also reduces cell proliferation in human mantle cell lymphoma and non-small-cell lung cancer (NSCLC) cell lines." (PMID 33922062, 2021).
Premature ovarian insufficiency (1 paper, 2023). Amenorrhea due to loss of ovarian function before the age of 40. "A recent study has implicated that loss of Lonp1, a mitochondrial protease compromises oocyte development and results in premature ovarian insufficiency." (PMID 37611828, 2023).
proteinopathies (1 paper, 2022). "Accordingly, loss of LONP1 has been shown to cause mitochondrial protein misfolding as part of proteinopathies, such as ALS and PD46,47; mutations in the import machinery (TIM and PAM complexes) are mostly lethal, but some have been described in multiple rare diseases." (PMID 36056001, 2022).
pulmonary fibrosis (1 paper, 2024). Chronic progressive interstitial lung disorder characterized by the replacement of the lung tissue by connective tissue, leading to progressive dyspnea, respiratory failure, or right heart failure. "Our study has shown that the loss of the Lonp1 gene exacerbates bleomycin-induced pulmonary fibrosis in mice." (PMID 38625722, 2024). "Collectively, these results indicated that the loss of Lonp1 leads to more severe pulmonary fibrosis." (PMID 38625722, 2024). "This study uncovers the role of the Lonp1 gene in pulmonary fibrosis, presenting a novel target for investigating the pathological mechanisms and potential therapeutic approaches for IPF." (PMID 38625722, 2024). "In this study, we examined the potential function of Lonp1 in IPF by establishing a mice model with AT2 cell-specific knockout of Lonp1 and inducing experimental pulmonary fibrosis using bleomycin." (PMID 38625722, 2024). "To investigate the role of Lonp1 in pulmonary fibrosis, we specifically knocked out the Lonp1 gene in AT2 cells by generating SftpcCreERT2; Lonp1flox/flox mice, as detailed in the Methods section." (PMID 38625722, 2024). "We generated a bleomycin-induced pulmonary fibrosis mouse model with a targeted Lonp1 knockout in AT2 cells and assessed the consequences on AT2 cell function and fibrosis progression." (PMID 38625722, 2024). "Therefore, loss of Lonp1 appears to promote AT2 cell aging and exacerbate bleomycin-induced pulmonary fibrosis." (PMID 38625722, 2024). "Our findings indicate that the absence of Lonp1 exacerbates bleomycin-induced pulmonary fibrosis, yet it remains uncertain whether LONP1 activators could be utilized as a therapeutic strategy for IPF." (PMID 38625722, 2024).
Salmonella Infections (1 paper, 2022). Infections with bacteria of the genus SALMONELLA. "We then measured the expression of various markers of the UPRmt, including the mitochondrial chaperone heat shock protein 60 and the mitochondrial proteases AFG3L2 and LONP1,24,27,28 in the presence or absence of Salmonella infection." (PMID 36516750, 2022).
sarcopenia (1 paper, 2022). Progressive decline in muscle mass due to aging which results in decreased functional capacity of muscles. "Notably, muscle-specific LONP1-knockout mice display many features of precocious aging including muscle atrophy and kyphosis further suggesting a possible link between impaired muscle mitochondrial protein quality with aging and sarcopenia." (PMID 35173176, 2022).
Stroke (1 paper, 2022). Sudden impairment of blood flow to a part of the brain due to occlusion or rupture of an artery to the brain. "Alterations in Lonp-1 are implicated in an array of human pathologies that include cancer, neurodegeneration, heart disease, and stroke." (PMID 36269765, 2022).
type 2 diabetes (1 paper, 2023). "Increased expression of HSP60, HSP10, LONP1 and ClpP protein was observed in the liver in an HFD-induced type 2 diabetes mouse model." (PMID 37095454, 2023).
cancer (36 papers, 2016 to 2025). A tumor composed of atypical neoplastic, often pleomorphic cells that invade other tissues. "Dysregulation of LONP1 has been implicated in various pathologies, including cancer, metabolic disorders, and reproductive diseases, positioning it as a promising pharmacological target." (PMID 40305312, 2025). "LONP1 is activated in various human cancer tissues, and its overexpression is associated with prognosis in multiple types of cancer." (PMID 39261452, 2024). "Here, we employed two experimental systems, the worm Caenorhabditis elegans and human cancer cells, to investigate and compare the effects of LONP-1/LonP1 deficiency at the molecular, cellular, and organismal levels." (PMID 35456042, 2022). "Cancer cells that are deficient in LonP1 have been found to exhibit a decreased capacity to proliferate." (PMID 36362158, 2022). "LonP1 is often overexpressed in aggressive tumors, and LonP1 deficiency has been associated with protection against other cancer types." (PMID 35456042, 2022). "On the other hand, pharmacological inhibition of LonP1 with the use of CDDO-Me caused an evident transcriptional activation of all stress response mechanisms studied here in both cancer cell lines." (PMID 35456042, 2022). "Accordingly, Lonp1 is upregulated in several types of cancer, and its higher expression has been associated with higher tumour aggressiveness both in vitro and in vivo." (PMID 36497197, 2022). "In contrast, LonP1-deficient cancer cells exhibit attenuated proliferation, increased apoptosis, decreased cellular bioenergy, and reduced drug resistance." (PMID 36362158, 2022). "Biallelic mutations in the LONP1 gene are known to cause a broad spectrum of diseases, and LonP1 dysregulation is also implicated in cancer and age-related disorders." (PMID 35151690, 2022). "Herein, we have investigated the effects of LonP1 deficiency at the molecular, cellular, and organismal levels in two experimental systems, the nematode C. elegans and human cancer cells." (PMID 35456042, 2022). "This is in line with previous observations that proved a higher metastatic potential of cancer cells expressing high levels of Lonp1 in vivo and with clinical data that, at least in some types of cancers, associated higher Lonp1 levels with a poorer prognosis." (PMID 36497197, 2022). "LonP1-deficient cancer cells exhibit attenuated cell proliferation, increased apoptosis, and reduced drug resistance in vitro." (PMID 36362158, 2022). "Second, the cancer-dependency map, a collection of large-scale loss-of-function screens, provides evidence that LonP1 and proteasomal subunits converge in a common pathway." (PMID 33671345, 2021). "Using two experimental systems, the nematode C. elegans and human cancer cells, we analyzed the cellular and organismal transcriptomic stress responses to Lonp1 deficiency caused by genetic and pharmacological approaches and how these affect physiological processes and phenotypes." (PMID 35456042, 2022). "In addition, cancer cells exposed to stress stimuli, including hypoxia, exhibit increased LONP1 expression associated with phosphorylation by the Akt pathway, which enhances oxidative metabolism and tumor cell metastatic competence." (PMID 33637676, 2021). "Conversely, studies have found increased expression of LONP1 in various cancer tissues, correlating with poor patient survival rates." (PMID 40332105, 2025). "Previously, researchers had identified functional crosstalk between LONP1 and ClpP, which are two mitochondrial matrix proteases that cooperate to attenuate proteotoxic stress and protect mitochondrial functions to promote cancer cell survival." (PMID 40083691, 2025). "Inhibitors such as CDDO and its derivatives selectively target LONP1, impairing mitochondrial proteolysis, inducing protein aggregation, and promoting apoptosis, particularly in cancer cells." (PMID 40305312, 2025).
cancer (continued). "Because of its multiple functions in the mitochondria, an impairment of Lonp1 activity or regulation has been observed in many pathophysiological conditions, including several types of cancer, neurodegenerative diseases, cardiovascular diseases, and aging." (PMID 40305312, 2025). "Such disruption of mitochondrial protein homeostasis can trigger oxidative stress, apoptosis, and cell death, particularly in cancer cells that are highly dependent on LONP1 for survival." (PMID 40305312, 2025). "Consistent with these cancer-related findings, we observed an up-regulation of LONP1 expression in lung tissues from two PH models and in PDGF-BB-induced PASMCs." (PMID 40332105, 2025). "This inhibition of LONP1 by (-)-sesamin leads to the induction of caspase-3-mediated apoptosis in various cancer cell lines, including NSCLC." (PMID 40305312, 2025). "This is illustrated by the altered expression and localization of MAM proteins in cancer cells, with LONP1 being a notable example." (PMID 39408926, 2024). "Several chemical inhibitors have the potential to inhibit LONP1 activity to prevent cancer progression and sensitize cancer cells to chemotherapy." (PMID 39261452, 2024). "Under hypoxic conditions, AKT1 phosphorylates LONP1 at Ser173 and Ser181 to enhance its protease activity, which attenuates ROS effects and promotes cancer cell migration." (PMID 39261452, 2024). "LONP1 also assists cancer cell migration and invasion by promoting CAFs formation in the TME and leads to PD-L1-mediated immune escape." (PMID 39261452, 2024). "Oxidative stress also induces LONP1 expression, which in turn promotes the proliferation and migration of cancer cells." (PMID 39261452, 2024). "Obtusilactone A and Sesamin, which inhibit LonP1 protease activity, were shown to reduce cancer cell proliferation and migration in lung cancer cells (A549 and H1299), with low cytotoxicity in healthy cells." (PMID 37445598, 2023). "Lonp1 overexpression has been observed in several cancers and has been shown to promote cell proliferation, apoptotic resistance to stresses, and the transformation of tumor cells." (PMID 36978846, 2023). "LonP1 is upregulated in many cancers, such as lung, breast, colon, prostate, stomach, glioma, pancreatic, endometrial, melanoma cancer and leukemia." (PMID 37445598, 2023). "As an independent prognostic factor for cancer, high levels of LonP1 are correlated with low survival." (PMID 36362158, 2022). "Several authors, including us, have shown an increase in Lonp1 expression in different cancer types." (PMID 36497197, 2022). "We also show that their expression is highly variable in cancer cells of different origins, suggesting a different biological role for Lonp1 isoforms in cancer development and progression." (PMID 36497197, 2022). "Lonp1 plays a key role in the metabolic reprogramming of cancer cells by remodelling OXPHOS complexes and protecting against senescence." (PMID 36497197, 2022). "Multiple studies have demonstrated that ClpP and LONP1 levels are markedly increased in numerous cancers." (PMID 35180892, 2022). "Accordingly, targeting ClpP and LONP1 is anticipated to reveal a new therapeutic perspective for cancer due to the oncogenic functions of these proteins." (PMID 35180892, 2022). "In vitro, LonP1 overexpression promotes the survival, proliferation, and migration of cancer cells, thereby triggering epithelial-to-mesenchymal transition." (PMID 36362158, 2022). "These compounds have been shown to promote cancer cell death, implicating LonP1 as an anticancer drug target." (PMID 35151690, 2022). "Recent studies have found that LonP1 affects the cancer phenotype by regulating the intracellular transport of mitochondria, and cell resistance to hypoxia." (PMID 36362158, 2022). "Several studies have proven that high levels of ClpP and LONP1 in colorectal cancer, prostate cancer, breast cancer and melanoma are notably correlated with poor prognosis in cancer patients." (PMID 35180892, 2022).
cancer (continued). "To corroborate our results from gene expression analysis in lonp-1 mutant worms, we surveyed a number of changes in response to mitochondrial LonP1 downregulation in human cancer cells." (PMID 35456042, 2022). "Subsequently, LONP1 ensures the stabilization of ETC complex II and complex V and, thus, protects cancer cells from damage caused by ROS accumulation." (PMID 35180892, 2022). "We evaluated the expression of the different Lonp1 isoforms in primary cells and cancer cell lines of different origins at transcriptional levels by ddPCR." (PMID 36497197, 2022). "Overall, the mitochondrial dysfunction ensued by disruption of LonP1 elicits adaptive cytoprotective mechanisms that can inhibit cancer cell survival but diversely modulate organismal stress response and aging." (PMID 35456042, 2022). "Cancer cells exploit the functions of ClpP and LONP1 in mitochondrial homeostasis and energy metabolism to accelerate their own invasion and metastasis." (PMID 35180892, 2022). "Emerging evidence suggests that inhibiting LonP1 or other quality control proteins in mitochondria and endoplasmic reticulum of cancer cells or immunosuppressor cells is a potential strategy for disabling oncogenic progression." (PMID 35151690, 2022). "LONP1 overexpression in cancer cells lowers the activities of Complexes I, II, III, and IV in conjunction with reduced mitochondrial respiration." (PMID 35864539, 2022). "LonP1 further contributes to the improved adaptation of cancer cells to stress in the microenvironment." (PMID 36362158, 2022). "In fact, ClpP and LONP1 coordinately regulate mitochondrial bioenergetics in cancer, which is reflected in the observation that ClpP and LONP1 have many common substrates." (PMID 35180892, 2022). "Because of its crucial role in mitochondrial homeostasis, Lonp1 can also contribute to neoplastic transformation and cancer progression." (PMID 36497197, 2022). "In our study, we found that SHMT2 is a common target substrate of LONP1 and ClpP for cancer cell survival." (PMID 33637676, 2021). "In this study, we found evidence of functional crosstalk between LONP1 and ClpP within the mitochondrial protein quality control pathway required for cancer cell survival." (PMID 33637676, 2021). "In summary, our study reveals a functional relationship between two mitochondrial proteases LONP1 and ClpP in maintaining mitochondrial proteostasis in cancer." (PMID 33637676, 2021). "Conversely, LonP1 overexpression promotes cancer cell proliferation, enhances colony formation, and more importantly, increases cellular resistance to apoptosis-inducing reagents." (PMID 33922062, 2021). "Conversely, the silencing of LONP1 and ClpP did not affect the growth of the non-cancerous cell lines BPH-1 and HEK-293, which had lower levels of LONP1 and ClpP than those in cancer cells." (PMID 33637676, 2021). "LONP1 and ClpP genes closely localized to chromosomal region 19 and were co-expressed at high levels in most human cancers." (PMID 33637676, 2021). "To investigate relationships between the two proteases, we first analyzed patterns of LONP1 and ClpP expression in various cancer types from The Cancer Genome Atlas (TCGA) database." (PMID 33637676, 2021). "Here, we identified functional crosstalk between LONP1 and ClpP, which are two mitochondrial matrix proteases that cooperate to attenuate proteotoxic stress and protect mitochondrial functions for cancer cell survival." (PMID 33637676, 2021). "Although LONP1 and ClpP exert similar actions in cancer, their regulatory mechanisms and potential interconnections remain largely unexplored." (PMID 33637676, 2021). "LONP1 and ClpP genes closely localized on chromosome 19 and were co-expressed at high levels in most human cancers." (PMID 33637676, 2021).